RECK (reversion inducing cysteine rich protein with kazal motifs)
Diseases named in the same sentence as RECK in open-access papers (continued):
Sharing a sentence is not in itself a finding about the gene and the disease.
cancer (continued). "miR-182 expression is induced by ß-catenin and in cancer cells contributes to invasiveness by down-regulating RECK, an inhibitor of extracellular metalloproteases." (PMID 28440221, 2017). "RECK expression is reduced in various cancer types including breast, colorectal, lung, pancreatic, prostate, and stomach cancer and cholangiocarcinoma, ameloblastic tumor, middle ear squamous cell cancer, and osteosarcoma." (PMID 28134767, 2017). "In the present study, we analyzed changes in the expression of RECK and associated Notch and VEGF signaling during the sequential progression of HBP carcinomas from hyperplasia through dysplasia and papillomas." (PMID 28515436, 2017). "We found a sequential increase in the expression of miR-21 during stepwise progression of HBP carcinomas, suggesting this as a possible mechanism for RECK downregulation." (PMID 28515436, 2017). "We report for the first time progressive Recklessness that correlated with increasing MMP expression during stepwise evolution of HBP carcinomas and upregulation of RECK following chemointervention with nimbolide." (PMID 28515436, 2017). "RECK, a recently characterized membrane bound protein, has been identified to play a pivotal role in cancer progression by limiting invasion, metastasis and angiogenesis of tumors." (PMID 27530410, 2016). "Specifically in the stomach, increased miR-222 expression in H. pylori infected AGS cells post-transcriptionally regulates RECK and promotes cancer-cell growth and invasion." (PMID 27323780, 2016). "In gene-focused studies, extensive methylation of RECK CpG island has been found in cancers of the colon, stomach, liver, and lung, and its correlation with poorer prognoses detected." (PMID 27058625, 2016). "It is known that histone deacetylation and promoter methylation are the mechanisms by which cancer cells act to suppress RECK expression." (PMID 25885317, 2015). "Previous reports have supported the potential role of RECK as a molecular marker for the prognosis of several cancer types." (PMID 26449734, 2015). "RECK is known to suppress migration and invasion of cancer cells, but the function of EVI5 is less clear." (PMID 25537516, 2015). "Further studies showed that RECK is down-regulated in many human cancers including pancreatic, breast, non-small cell lung cancer and osteosarcoma and in cells that ectopically express active oncogenes." (PMID 25885317, 2015). "The positive expression of RECK protein was mainly located in the cytoplasm of carcinoma cells, demonstrated by a pale yellow or buff color." (PMID 24765174, 2014). "This membrane-anchored matrix metalloproteinase-regulator is frequently down regulated in cancers and a significant correlation exists between the level of residual RECK expression in resected tumors and patient survival." (PMID 24265725, 2013). "In cancer cells, the repression of RECK by hypoxia also influenced cell proliferation and enhanced migration or invasion." (PMID 24376819, 2013). "The micro RNA (miRNA) mir-21 has been shown to regulate invasiveness in cancer through translational repression of the Metaloproteinase (MMP) inhibitor RECK." (PMID 22642976, 2012). "As reviewed by Noda and Takahashi, RECK is described as a good prognosis marker, and several prior reports have demonstrated that RECK expression is decreased during cancer progression." (PMID 22260435, 2012). "A total of 135 HCC cancer patients and 501 cancer-free controls were analyzed for four RECK SNPs (rs10814325, rs16932912, rs11788747, and rs10972727) using real-time PCR and PCR-RFLP genotyping analysis." (PMID 22428065, 2012).
cancer (continued). "Down-regulation of RECK has been documented in many human cancers, including various carcinomas, and correlates with aggressiveness and poor prognosis of the disease." (PMID 22438955, 2012). "The membrane-anchored matrix metalloproteinase-regulator RECK is often down-regulated in various types of cancers; the levels of residual RECK in resected tumors often correlate with better prognosis." (PMID 21304177, 2010). "RECK encodes a glycosylphosphatidylinositol (GPI)-anchored glycoprotein of ~125 kDa, which inhibits at least four cancer-associated MMPs, i.e., MMP-2, MMP-7, MMP-9, and MT1-MMP." (PMID 21304177, 2010). "RECK is therefore a useful marker for benignancy and a promising target (or effector) to be activated in cancer therapy." (PMID 21304177, 2010). "The appearance of unmethylation-specific bands of RECK gene in all four cancer cell lines became more intense after treatment with 50 μM EGCG or 8.7 μM 5-aza-dC for 6 days." (PMID 18665171, 2008). "In all cancer cell lines, the RECK gene had hypermethylation status with the low level of the respective mRNA expression." (PMID 18665171, 2008). "RECK has been shown in studies of wound healing and cancer metastasis to be a key regulator of the extracellular matrix integrity and an inhibitor of angiogenesis." (PMID 18000554, 2007). "In the meantime, mechanisms by which RECK expression is reduced in cancer cells have been explored." (PMID 41598259, 2026). "Furthermore, recent findings in the clinic as well as in animal studies indicate the involvement of RECK in disorders other than cancer." (PMID 41598259, 2026). "RECK was first reported as a transformation suppressor gene in 1998 and gradually gained attention as evidence indicating its reduced expression in a wide variety of human cancers accumulated." (PMID 41598259, 2026). "RECK is downregulated in various human cancers; however, how RECK inactivation affects carcinogenesis remains unclear." (PMID 37712427, 2023). "Additionally, we observed the same low expression of RECK protein levels in pan-cancer datasets from the CPTAC database." (PMID 37904179, 2023). "RECK downregulation occurs in many cancer types and is often correlated with a poor prognosis." (PMID 37712427, 2023). "The HPA database was utilized to describe the expression of RECK in pan-cancer tissue." (PMID 37255541, 2023). "RECK mutations, however, are rare in cancer genomes, suggesting that RECK expression is transcriptionally and/or epigenetically suppressed and agents that can re-activate dormant RECK in cancer cells may be of clinical value." (PMID 35149728, 2022). "Lower RECK expression in cancer cells is frequently accompanied by epigenetic modifications, such as DNA methylation, and whether M. pneumoniae reduces RECK expression through methylation remains to be determined." (PMID 35892136, 2022). "The KEGG pathway data showed the involvement of ZEB1 and RECK in microRNA networks in cancer." (PMID 35098570, 2022). "Although the influence of RECK has been studied in various cancers, its role in UTUC remains unclear." (PMID 33987019, 2021). "When RECK is downregulated in human cancers, transcription or epigenetic changes occur." (PMID 32522890, 2020). "RECK in cancer can be targeted by certain oncogenic miRNAs, such as miRNA-182-5p and miR-25." (PMID 32138716, 2020). "The miR-21/RECK axis can support the previous finding that curcumin inhibits cancer metastasis." (PMID 33066509, 2020). "PTEN and PDCD4 have been previously shown to impede cancer cell growth and facilitate apoptosis, while RECK could reduce cancer cell mobility by deactivating matrix metalloproteinases." (PMID 30736829, 2019). "Three variants in RBM12, one variant in NDUFB6, ten variants in DLGAP4-AS1, five variants in ATPV1A, eleven variants in RECK, four variants in SLC35E1, eight variants in RFX3, and eight variants in ATP8A1 were known somatically acquired mutations in various cancers." (PMID 31338326, 2019).
cancer (continued). "Other variants in intron, splicing region and UTR region could also promote cancer by downregulating canonical RECK isoform or alternative splicing of RECK, producing the shorter isoform." (PMID 31338326, 2019). "Using zebrafish-human comparative oncogenomics, on human chromosome 9p, we have identified the RECK gene as a cancer driver candidate that could potentially be a tumor suppressor gene for MPNSTs." (PMID 29805750, 2018). "Identification of other TSGs on the chromosome 9p might further help to understand the tumorigenic mechanism of RECK and to develop new cancer treatment strategies based on the concept of gene cooperation." (PMID 29805750, 2018). "Up-regulation of RECK expression by HDAC inhibitors has been observed in various cancer types." (PMID 28134767, 2017). "In addition, RECK expression is positively correlated with the survival of cancer patients; down-regulation of RECK often predicts poor prognosis in cancer patients." (PMID 28134767, 2017). "Collectively, HDAC inhibitors may directly induce ER stress or indirectly induce stress by up-regulating RECK in cancer cells." (PMID 28134767, 2017). "Studies on the mechanism of action of MS275 in RECK-upregulation may also provide some clues to better understanding how RECK can be repressed in cancer cells." (PMID 27058625, 2016). "However, the loss of E-cadherin expression by TGF-β1 treatment is uncoupled from RECK upregulation in different carcinoma-derived cell lines." (PMID 26247610, 2015). "Interestingly, immunohistochemical analysis in human cervical tissues show a decrease of RECK levels in precancer and cancer lesions." (PMID 22438955, 2012). "Finally, a study conducted in human cervical tissues showed a decrease in RECK expression levels in precancer and cancer lesions." (PMID 22438955, 2012). "Therefore, the up-regulation of the RECK expression is considered potentially as a therapeutic approach to limit cancer angiogenesis and metastasis by suppressing vessel branching via MMPs inhibition." (PMID 21573219, 2011). "Although RECK is expressed ubiquitously in normal human organs, it is down-regulated in cancers of many organs including those of the lung (non-small cell type), colorectum, breast, and pancreas, in which the prevalent mechanism is probably epigenetic silencing rather than genetic mutations." (PMID 21304177, 2010). "Four selected compounds up-regulated endogenous RECK protein in several human cancer cell lines." (PMID 21304177, 2010). "RECK is therefore a promising marker for benignancy and a potential effector in cancer therapy." (PMID 21304177, 2010). "In conclusion, our findings raise the possibility that EGCG could inhibits cancer cell invasion through reversal of hypermethylation status of RECK and downregulation of MMP-2 and MMP-9." (PMID 18665171, 2008). "In contrast, there was significantly decreased expression of MMP2 and MMP23, maspin, and the protease inhibitors tissue inhibitor of metalloproteinase 3 (TIMP3), TIMP4 and RECK (reversion-inducing cysteine-rich protein with Kazal motifs) in the cancer specimens." (PMID 15928670, 2005). "Furthermore, the upregulation of RECK may be a promising approach for treating malignant tumors, also considering the RECK gene as a promising target for the prevention and treatment of hepatic cancer invasion and metastasis." (PMID 38139236, 2023). "Therefore, HDAC inhibitors may directly induce ER stress or indirectly induce this stress by up-regulating RECK in cancer cells." (PMID 28134767, 2017). "However RECK has been reported to decrease cell proliferation in other cancers." (PMID 23383207, 2013). "Therefore, the induction or over expression of RECK by drug may be considered as an anti-angiogenic or anti-cancer approach." (PMID 21573219, 2011).
cancer (continued). "To verify the selected DEM (hsa-miR-21-5p), DEL (MIR99AHG) and 5 DEGs (RECK, TIMP3, EHD1, ERG and RASGRP1), we collected sequencing data from several cancer and normal tissues to explore the expression levels of these RNAs." (PMID 38495494, 2024). "The activities of the cancer immunity cycle also confirmed that T-cell recruitment and CD4+ T-cell recruitment from step 4 were upregulated in the high RECK expression group, as well as infiltration of immune cells into tumors." (PMID 37904179, 2023). "Accordingly, over-expression of miR-21 in human cancers results in a decreased level of the tumor-suppressor proteins PTEN, PDCD4, SPRY2, and/or RECK, thereby promoting cell proliferation." (PMID 34066762, 2021). "These suggest that RAP1A, STARD13, SASH1, RECK, and CBFA2T3 had big positive network effects on down-expression of genes in stage-3 cancer." (PMID 33580150, 2021). "RECK is a membrane-anchored MMP inhibitor that negatively regulates activities of MMP-2 and MMP-9, and consequently reduces cancer invasion and metastasis." (PMID 32349289, 2020). "MiR-21-5p is a well-studied “oncomiR” in multiple types of cancers with PTEN, PDCD4 and RECK as its best-known target genes." (PMID 30736829, 2019). "Measurements of the expression of RECK and MMP-2 are valuable, not only to assess patient prognosis, but to also develop new strategies for cancer prevention and therapeutic intervention." (PMID 24765174, 2014). "SPARC, RECK, TNFAIP3 and CXCL14 were down-regulated (p < 0.05) in BCBM as compared to primary BC samples irrespectively of the cancer subtype, while for CADM1, this correlation was found in HR positive and TNBC samples." (PMID 24833255, 2014). "An increase in the TIPM3 and RECK protein levels (3.21- and 1.35-fold increase respectively) and a decrease in the MMP2 protein level (0.46-fold) indicated that overexpression of CLEC19A reduced the ability of U87 cancer cell migration." (PMID 38167030, 2024). "Efficient knockdown of miR-21 by CHAIN restored programmed cell death protein 4 (PDCD4) and reversion‐inducing‐cysteine‐rich protein with Kazal motifs (RECK) and further crippled downstream matrix metalloproteinases-2 (MMP-2), which undermined cancer proliferation, migration and invasion." (PMID 37284454, 2023). "Moreover, the KEGG analysis showed that RECK and E2FI in the MEbrown module are enriched in the pathways related to miRNA in cancer." (PMID 35123404, 2022). "Significantly altered functions, pathways, and gene networks revealed alterations in several key genes and cancer-related pathways that may have importance for NSCLC transformation, including FAM83A, ZNF696, UBE2C, RECK, TIMM50, GEMIN7, and XPO5." (PMID 35309509, 2022). "At stage 3, STARD13, CBFA2T3, RECK, and SASH1 had strong accordant/discordant effects on expression of genes in cancer, while APC, EXT1, NBL, KLK10, and PTCH1 had very weak accordant/discordant impacts on expression of genes in cancer." (PMID 33580150, 2021). "Hence, the strong TS genes SASH1, STARD13, RECK, CBFA2T3, RASSF2, RAP1A, and ARHGEF12 can be used as specific biomarkers for diagnosis of NSCLC cancer." (PMID 33580150, 2021). "miR-21 stimulates cancer cell proliferation, inhibits apoptosis, and increases invasion and metastasis by targeting multiple molecules such as programmed cell death (Pdcd4), the phosphatase and tensin homolog gene (PTEN), and RECK." (PMID 32349289, 2020). "Reversion-inducing cysteine-rich protein with Kazal Motifs (RECK) is known to suppress proliferation, invasion, and metastasis primarily through inhibiting matrix metalloproteinases (MMPs), such as MMP-2 and MMP-9, in multiple cancer types." (PMID 33066509, 2020). "As so many cancer-related genes including VEGF, E-cadherin, RECK, and integrin α5 can be regulated by Sp1, there may be other effector molecules implicated in AGEs/RAGE/Sp1 cascade which mediated gastric metastasis." (PMID 29262634, 2017).
cancer (continued). "Targets of miR-21 in cancer include PTEN, PDCD4, LRRFIP1, RECK, TIMP-3, TPM1, BTG2, and Sprty2." (PMID 25366985, 2014). "RECK is expressed in various normal human tissues, but has not been detected in oncogenically transformed cells and in various type of cancers, such as, hepatoma, pancreatic, breast, lung, colorectal, prostate, and gastric cancer, or in osteosarcomas." (PMID 24376819, 2013). "RECK decreases the amount of active MMP-2 and MMP-9 in conditioned medium and inhibits metastatic activity in vitro and in vivo through modulation of these MMPs, which are known to be involved in cancer progression." (PMID 22642976, 2012). "Recently miR-21 was identified as a regulator of RECK gene expression in several cancers, but to date there has been no report showing direct regulation of RECK by miR-182-5p." (PMID 23226455, 2012). "In the present study, we report that EGCG, a major component of green tea, may enhance RECK expression by reversal of hypermethylation of RECK promoter and inhibit MMP activities as well as cancer cell invasion in OSCC cell lines." (PMID 18665171, 2008). "Moreover, gene interaction networks revealed several key genes and cancer-related pathways that may role for early NSCLC transformation and disease progression, including FAM83A, ZNF696, UBE2C, RECK, TIMM50, GEMIN7, and XPO5." (PMID 35309509, 2022). "It has been widely established that miR-21 promotes survival and proliferation of cancer cells by directly inhibiting its targets, including PTEN, Programmed Cell Death 4 (PDCD4), reversion-inducing-cysteine-rich protein with kazal motifs (RECK), and sprouty RTK signaling antagonist 2 (SPRY2)." (PMID 34066762, 2021). "Moreover, unlike other cancer types, previous results from our laboratory showed that RECK transcript levels are higher in highly invasive and metastatic cell lines compared to less aggressive breast cell lines." (PMID 22260435, 2012). "Pathway enrichment analysis (KOBAS 3.0) of the genes in the MEbrown module showed that RECK and E2F1 were enriched in the miRNA in cancer pathway (p < 0.05), with no significant enrichment detected for the other genes." (PMID 35123404, 2022).
infection (3 papers, 2009 to 2022). The state of being infected such as from the introduction of a foreign agent such as serum, vaccine, antigenic substance or organism. "In insect hemocytes, MMPs may be required for tissue transmigration to reach the site of infection or to activate cytokines or antimicrobial peptides, similar to what has been recently shown for mammalian lymphocytes, whereas TIMP and RECK may have regulatory functions." (PMID 19270735, 2009). "Moreover, RECK regulates MMP9 and exerts its effects primarily through suppression of WNT7A/WNT7B, but regulation of neither Wnt7a nor Wnt7b regulation was observed in our gene microarray dataset, and scRNA-Seq did not detect Wnt7a nor Wnt7b expression, before or after infection, in any ME cells." (PMID 36092940, 2022).
cardiovascular diseases (2 papers, 2021 to 2024). "Reversion-Inducing-Cysteine-Rich Protein with Kazal Motifs (RECK) is a membrane-anchored glycoprotein that modulates matrix metalloproteinases (MMPs) and is closely linked to inflammatory responses in cardiovascular diseases." (PMID 39742258, 2024). "The alteration of MMPs-Long RECK interaction and the consequent release of MMPs, an enhanced expression and/or activation of MMPs, and the alteration of ECM components, are all events associated with the pathogenesis of cardiovascular diseases." (PMID 34205376, 2021).
adenocarcinoma (1 paper, 2013). A common cancer characterized by the presence of malignant glandular cells. "In the case of RECK, CRISPLD2, HPGD, GATA3 and GPC3, the signal related to the expression of the protein was down regulated in more than 45% of adenocarcinomas compared to surrounding healthy pneumocytes." (PMID 24265725, 2013).